TNF (tumor necrosis factor)
Diseases named in the same sentence as TNF in open-access papers (continued):
Sharing a sentence is not in itself a finding about the gene and the disease.
lupus (continued). "The aim of this study was to explore potential relationships between sera TNF-α levels and mood and anxiety disorders in systemic lupus erythematosus (SLE) patients." (PMID 26732584, 2016). "Monotherapy of systemic lupus erythematosus (SLE) patients with chloroquine results in a decrease in serum levels of IL-6, IL-18, and TNF-α." (PMID 25348033, 2014). "Serum soluble receptor of TNF-α was elevated in 12 patients with active lupus nephritis compared with inactive SLE and healthy subjects and declined after clinical remission." (PMID 24692841, 2014). "Anti-TNF-α may additionally trigger systemic autoimmune diseases as systemic lupus erythematosus." (PMID 24707429, 2014). "A previous study demonstrated that TNF −238A/G was associated with systemic lupus erythematosus in Caucasian populations, not in African and Mexican populations, suggesting the interactions between different environments and gene might be different." (PMID 24049437, 2013). "Systemic lupus erythematosus (SLE) patients frequently have high circulating tumor necrosis factor alpha (TNF-α) levels." (PMID 24187561, 2013). "It has been proposed that this polymorphism ameliorates murine lupus symptoms and, indeed, it has been shown by Kontoyiannis and Kollias, that autoimmunity and lupus nephritis is accelerated in NZB mice with an engineered heterozygous deficiency in tumor necrosis factor." (PMID 22761632, 2012). "We then examined the relationship between the level of pro-inflammatory cytokines (that is, IFN-α and TNF-α) produced by pDCs and the clinical activity of SLE (as defined using the Systemic Lupus Activity Questionnaire, or SLAQ)." (PMID 22734582, 2012). "Thus, independently or synergistically, these and other factors may contribute to the magnitude of TNF-α production by lupus monocytes." (PMID 21423726, 2011). "In addition, TNF-α is a crucial mediator of lung injury in experimental lupus." (PMID 21637713, 2011). "The TNF/TNF-receptor system appears to play an important role in SLE pathogenesis, as is exemplified by TNFα-induced amelioration of murine lupus nephritis and an increased soluble TNF-receptor correlation with disease activity." (PMID 19563672, 2009). "We report on 22 patients treated with anti-TNF alpha for severe RA or psoriatic arthritis (15 patients receiving infliximab and seven patients receiving etanercept) with no previous sign of lupus disease who developed clinical and biological manifestations of drug-induced lupus." (PMID 15899041, 2005). "We report here the results of a French national survey revealing 22 cases of drug-induced lupus erythematosus (systemic lupus erythematosus [SLE]) in French patients being treated with anti-TNF alpha for inflammatory arthritides." (PMID 15899041, 2005). "Recruitment of neutrophils to the skin is mediated by pro-inflammatory cytokines and chemokines, such as TNF-α, IL-8, and CXCL8, which are elevated in lupus lesions." (PMID 41375587, 2025). "The three Lactobacillus strains improved hepatic injuries and reduced inflammation in lupus-prone mice by suppressing MAPK/NF-κB signaling pathways and lowering IL-1β, IL-6, and TNF-α expression." (PMID 40534849, 2025). "In systemic lupus erythematosus (SLE), dysregulation of TNF-α significantly contributes to the tissue damage that characterizes the systemic nature of the disease." (PMID 41009491, 2025). "While both agents share similar pathways such as TGF‐β and systemic lupus erythematosus, they also exhibit unique molecular actions, particularly in the MAPK pathway for Dex and the stem cell regulation and TNF pathways for TPO." (PMID 40251893, 2025). "In systemic lupus erythematosus (SLE), LDGs exhibit a strong pro-inflammatory role by inducing T cells to release IFN-γ, TNF-α, and lymphotoxin alpha (LTA)." (PMID 40689395, 2025). "NK-cells play diverse functions in murine lupus producing cytokines such as IFN-γ, TNF-α, GM-CSF, interleukin (IL)-10, and IL-13 upon stimulation." (PMID 40806179, 2025).
lupus (continued). "Regarding systemic lupus erythematosus (SLE), anti-TNF therapy is rarely used due to the potential induction of lupus-like syndromes, although etanercept has occasionally been employed with some success for refractory arthritis in clinical observational studies." (PMID 41009491, 2025). "Purified human CD4+ T cells stimulated with anti-CD3 and anti-CD28 antibodies exhibited robust production of lupus-related pro-inflammatory cytokines (e.g., IFN-γ, TNF-α, IL-5, and IL-6) upon anti-CD3/CD28 beads stimulation." (PMID 39551768, 2024). "In addition, systemic lupus erythematosus is associated with dysbiosis and, on the one hand, increased intestinal secretion of IL-17 and IL-22 from T cells and IFN-α and IFN-β from dendritic cells, and, on the other hand, systemic secretion of IL-6 and TNF-α by monocytes and macrophages." (PMID 39273791, 2024). "Different immunosuppressants have their concerns: systemic glucocorticoids nonspecifically decrease the immune system and may have a negative impact on anti-tumor immunity, whereas TNF inhibitors can be worrisome to use for ICI-LE as they themselves can cause drug-induced lupus." (PMID 38399467, 2024). "We demonstrated enhanced chromatin accessibility surrounding genes involved in lymphocyte activation, TNF-α signaling, and IFN-α and IFN-γ responses in lupus Th cells." (PMID 39688922, 2024). "Gene set variation analysis (GSVA) was used to measure enrichment of these pathways in individual lupus participants and cell subsets, and IFN-γ, TNF-α, and IFN-α pathways were transcriptionally enriched in lupus naive, AcTfh, and cTfh cell subsets." (PMID 39688922, 2024). "The search strategy incorporated the following keywords: "drug-induced lupus", "DIL", and "TNF inhibitors (TNFi)"." (PMID 39606520, 2024). "Our findings reveal that EA treatment inhibited IFN‐γ and TNF‐α production by CD8+ T cells in the uterus of pregnant lupus mice and improved the placental damage in lupus mice, thereby revealing the putative therapeutic benefit of EA in pSLE disease." (PMID 37771913, 2023). "Another adverse effect of TNF-α inhibitors is the onset of induced iatrogenic lupus (ATIL, anti-tumor necrosis factor-alpha-induced lupus)." (PMID 36836166, 2023). "In lupus mice, there was impaired in vivo homing capacity of SLE BMSCs upon TNFα stimulation, evidenced by massively trapped BMSCs within the lungs." (PMID 38164134, 2023). "In a study on pristane-induced lupus in BALB/c mice, baicalin reduced the production of proinflammatory cytokines such as TNF-α, IL-6, IL-10, and IFN-γ." (PMID 37511964, 2023). "Dalazatide, a Kv1.3 channel inhibitor currently in clinical trials, has been reported to reduce inflammatory cytokines such as IFN-γ, IL-17, and TNF–α in CD4+ and CD8+ T cells from patients with systemic lupus erythematosus (SLE)." (PMID 37033961, 2023). "The MSCs overexpressing IL-37 decreased the levels of IL-1, TNF-α, IL-17, IL-6, anti-dsDNA, and anti-ANA in systemic lupus erythematosus mice." (PMID 35935954, 2022). "Pro-inflammatory cytokines IL12 and TNF were highly expressed in CLE, supporting the role of these genes in mediating lupus pathogenesis." (PMID 35280134, 2022). "Following univariable and multivariable logistic regression analysis, TNF RII and MIP-1b were enrolled in the diagnosis model, and TNF RII, BLC, and MIP-1b were enrolled in the active lupus diagnosis model." (PMID 35966818, 2022). "According to available studies, the serum-soluble TNF RII level was higher in patients with SLE than in healthy volunteers, not only at the time of diagnosis but also at the time of posttreatment, and it showed a significant correlation with lupus disease activity." (PMID 35966818, 2022). "TNF RII, BLC, and MIP-1b showed statistical significance in logistic regression analysis in differentiating active lupus from inactive lupus." (PMID 35966818, 2022).
lupus (continued). "In the LFRR cohort, IL-10 was highest in lupus relatives who were clinically unaffected, while active TGF-β, as well as IFN-γ and TNF-α, were elevated in lupus relatives with ILE." (PMID 35720322, 2022). "Immune complexes, autoantibodies, and various cytokines (TNF-α, MCP-1, IL-6, IL-8, IL-17, IL-12, and IL-18) are responsible for vascular endothelial injury in lupus." (PMID 35795725, 2022). "The lupus-induced increase in interferon α (IFN-α), IL-6, and TNF-α levels was improved by resveratrol, as well as the renal manifestation, such as proteinuria." (PMID 35631330, 2022). "LDGs from patients with SLE (systemic lupus erythematosus) induced T cells to produce significantly higher levels of interferon gamma (IFN-γ) and tumor necrosis factor alpha (TNF-α), two proinflammatory cytokines, compared to NDNs." (PMID 34578124, 2021). "In patients with systemic lupus erythematosus (SLE), exogenous TNF-α can restore the expression of PD-L1 in lupus cells, while TGF-β, on the contrary, can inhibit the expression of PD-L1 in lupus cells." (PMID 35069596, 2021). "Their study suggested that GPER1 provoked the expression of classic inflammation cytokines tumor necrosis factor α (TNF-α) and monocyte chemoattractant protein-1 (MCP-1) and induced monocytosis in systemic lupus erythematosus (SLE)." (PMID 34239558, 2021). "Evidence showed that several proinflammatory cytokines, e.g., TNF-α, GM-CSF, and IFN-γ, significantly elevated in the circulation of lupus patients, which formed a microenvironment to facilitate macrophage polarization towards M1." (PMID 32775470, 2020). "In the current study, we demonstrated that IL-Y aggravated the progression of cGVHD by activating T and B cells, and increasing TNF-α secretion by CD4+ and CD8+ T cells in scleroderma-like and lupus-like cGVHD models." (PMID 33329519, 2020). "Therefore, increased TNF expression in Sh3bp2 gain-of-function mutant cells might aggravate inflammation in arthritic conditions while alleviating immunological and pathological symptoms in lupus-like conditions." (PMID 31052273, 2019). "To investigate the cytokine release by macrophages stimulated with lupus IgG, we detected TNF-α and MCP-1 levels in the supernatant of BMMs stimulated with lupus IgG." (PMID 32082297, 2019). "Of this proinflammatory cytokines, IL-6, IL-17, TNF-α, and IFN-α suppression have been reported as therapeutic targets for clinical management of lupus and other chronic inflammatory diseases." (PMID 31781106, 2019). "We found that lupus IgG increased the levels of TNF-α and MCP-1, whereas Syk inhibitor treatment significantly inhibited TNF-α and decreased MCP-1 expression, but the difference in MCP-1 expression was not significant." (PMID 32082297, 2019). "Although many phenotypes can be attributed to increased TNFα signaling in the ABIN1 model, it seems unlikely that this is the mechanism of the lupus-like phenotypes." (PMID 31354711, 2019). "Activation of miR-654 reduced IL-1β, IL-6, IL-8, and TNF-α production, reduced gomerulonephritis, and decreased MIF, IgG, and C3 expression in murine lupus glomeruli." (PMID 31608058, 2019). "We further determined the role of TNF-α and IFN-γ in hepatocyte apoptosis induced by lupus-IgG in vivo." (PMID 29988500, 2018). "KEGG analysis revealed the systemic lupus erythematosus pathway involving CD86, TNF, C4, FCGR2B, CD80, C3, CD40, and C1S." (PMID 28976997, 2017). "CXCL10 is induced by type I and II IFNs as well as TNF, and has been evaluated as a surrogate biomarker to reflect the IFN signature upregulated in autoimmune rheumatic diseases including RA and systemic lupus erythematosus (SLE)." (PMID 27102921, 2016). "Non-classical monocytes were observed to preferentially produce TNF and CCL3 in serum from individuals with lupus." (PMID 27097224, 2016). "Our study also confirms and strengthens previous reports on increased levels of IL-6, IL-10, TNF-α, IFN-γ, IL-17 and IL-23 as well as low TGF-β in lupus patients." (PMID 25887118, 2015).
lupus (continued). "Expression of mRNA for TNF-α, IL-1β, and CCL2 in kidney tissue was reduced in both strains of lupus-prone mice following treatment with ISO-1." (PMID 26617609, 2015). "Multiple cytokines have been implicated in playing key roles during the initiation, progression, and development of murine and human lupus including, but not limited to, IFN-, IL-17, IL-6, IL-1 and TNF-′." (PMID 25867237, 2015). "One of the pro-inflammatory cytokines thought to be related to the pathogenesis of systemic lupus erythematosus (SLE) and other inflammatory diseases is tumor necrosis factor-α (TNFα)." (PMID 26391351, 2015). "TNF-α blockage may induce autoimmune phenomena in individuals with some genetic background as confirmed by the onset of autoantibodies (50% of antinuclear antibodies and 15% of anti-DNA antibodies), drug induced lupus, vasculitis, antiphospholipid syndrome, and other autoimmune entities." (PMID 24600322, 2014). "In contrast, TNF-α concentration was elevated in sera and renal tissue of MLR/lpr lupus mice and the levels of this cytokine correlated with the severity of kidney disease." (PMID 24917428, 2014). "Small scale clinical trials in human SLE suggest that short-term TNF-α blockade may have benefit in lupus nephritis, as well as transient benefit in SLE arthritis." (PMID 24187561, 2013). "CD40L, a member of the tumor necrosis factor (TNF) ligand family, is overexpressed in patients with systemic lupus erythematosus and in lupus mouse models." (PMID 24627791, 2013). "The role of TNFα, HSP70, or MHC class II gene loci in lupus pathology is more difficult to evaluate." (PMID 22761632, 2012). "In different strains of lupus mice, the expression of TNF-α is often variable, and beneficial effects on the disease can be observed either after administration of TNF-α or upon TNF-α blockade." (PMID 22500177, 2012). "Symptoms occur after prolonged anti-TNFα therapy (mean 40.6 weeks) and they are characterized, as in classic DILE, by generalized symptoms, musculoskeletal manifestations, lupus-like cutaneous features and the appearance of serum autoantibodies." (PMID 22937775, 2012). "Thus the blockade of TNF-α itself may favor a lupus-like autoimmunity phenomenon." (PMID 22192852, 2011). "In some lupus models (e.g. the NZB x NZW F1 mouse), reduced levels of TNF-α are observed, and replacement therapy with recombinant TNF-α induces a significant delay in the development of nephritis." (PMID 21423726, 2011). "It was found that TNF-α, IL-1β, IL-6, IL-12 and MCP-1, which were upregulated in kidneys of ALD-DNA-induced lupus mice, were decreased in the pSAP-treated lupus mice." (PMID 21799927, 2011). "Analysis of the cytokine profile in serum of mice further confirmed that the inflammatory markers (including TNF-α, IL-1β, IL-6, IL-12, and MCP-1) were extensively and dramatically decreased in pSAP-treated lupus mice as compared with other control groups." (PMID 21799927, 2011). "In another model, elicited peritoneal macrophages from lupus-prone New Zealand Black/White F1 (NZB/W) mice showed a unique cytokine production profile, with a higher amount of IL-6 and about a half amount of TNF-alpha following stimulation with DNA." (PMID 27713252, 2010). "For instance, in the circumstances of autoimmune diseases (systemic lupus erythematosus [SLE] and RA) or AD, B cells are driven to differentiate into age‐related phenotype by abnormally accumulated proinflammatory factors such as IL‐6 and TNF‐α." (PMID 41427020, 2025). "Several mechanisms have been proposed to explain TNF inhibitor–induced lupus, though none have been definitively established." (PMID 41375587, 2025). "Conversely, TNF blockade triggers IFN-I overexpression in pDCs and lupus-like symptoms." (PMID 40796660, 2025).
lupus (continued). "Bregs, in addition to restraining the production of IFN-α from pDCs through IL-10 release, act under normal circumstances to suppress T helper cells and prohibit the production of cytokines such as TNF-α and IFN-γ, an ability that Bregs from lupus patients seem to lack." (PMID 39456692, 2024). "By GSVA using lupus-relevant murine gene sets, MRL/lpr mice showed increased enrichment of a number of inflammatory cell and cytokine gene sets including T cells, myeloid cells, neutrophils, pDCs, IFN, IL1, IL21, and TNF." (PMID 38860651, 2024). "We identified robust transcriptional enrichment of the TNF-α signaling pathway in group 1 patients with lupus and not in either group 2 patients with lupus or HCs." (PMID 39688922, 2024). "It is hypothesized that the administration of TNF-α inhibitors may result in an unregulated increase in IFN-α, which in turn may induce lupus-like reactions." (PMID 39618670, 2024). "The correlation between gut mycobiota and lupus characteristics, including anti-dsDNA, urine protein creatinine index (UPCI), and serum cytokines (IL-6, TNF-α, and IL-10) were examined using the NMDS with length and direction of vectors to represent strength and direction of the association." (PMID 39637140, 2024). "Instead, most RA patients respond well to TNF blockers, while patients with systemic lupus erythematosus (SLE) do not." (PMID 38994353, 2024). "In parallel with the epigenetic landscape, patients with lupus prescribed ARBs lacked TNF-α signaling enrichment." (PMID 39688922, 2024). "For example, in non-lupus controls, modules such as IFN, plasma cell, IG chains, myeloid cell, and tumor necrosis factor (TNF) tended to have GSVA scores less than zero, whereas modules such as B cell, T cell, and T cell chains (TCRA, TCRAJ, TCRB, TCRD) tended to have GSVA scores greater than zero." (PMID 37845772, 2023). "Before starting anti‐TNF medication, baseline immunological tests (including those for antinuclear antibodies [ANA]) must be performed, and patients should be closely monitored for the emergence of lupus symptoms." (PMID 37476595, 2023). "Naja naja atra snake venom and its toxin neurotoxin-Nna has been shown to decrease IL-1β and TNF-α levels in the kidney and the serum of rats, respectively; in addition, N. n. atra venom can inhibit IL-6 and TNF-α production in systemic lupus erythematosus in mice." (PMID 36828473, 2023). "Moreover, the pathophysiology of anti‐TNF in the emergence of SLE remains unclear, and several theories have attempted to explain the prevalence of lupus or lupus‐like symptoms in patients receiving anti‐TNF medication." (PMID 37476595, 2023). "Some anti-TNF-induced pulmonary complications have been identified: infections (TB, bacterial and fungal infections), exacerbations of underlying lung disease, interstitial lung disease (ILD), granulomatous lung disease, systemic lupus erythematosus (SLE)-like reactions and vasculitis." (PMID 37835065, 2023). "First, although TNF‐induced lupus primarily causes musculoskeletal and cutaneous manifestations (as seen in our patient), neurological lesions in TNF‐induced lupus are exceedingly unusual and nonspecific." (PMID 37476595, 2023). "We demonstrated that IL-39 could play a pathogenic immune role by increasing the proportion of Th2 cells and secretion of TNF-α in CD4+ and CD8+T cells in scleroderma-like and lupus-like cGVHD models." (PMID 35655245, 2022). "Nevertheless, the origins of the autoantibodies that arise in patients treated with TNF inhibitors and the reason why only a few of these patients develop clinical lupus have not been fully explored." (PMID 35104241, 2022). "The mechanism responsible for the development of lupus-like reactions in patients treated with TNF-α inhibitors has not been established." (PMID 35884790, 2022).